ENSG00000284779 (novel protein)
Gene: Protein-coding gene on chromosome 11 (2,131,395 to 2,149,603, reverse strand). Ensembl gene ENSG00000284779.
Gene Ontology:
Molecular function: hormone activity; insulin receptor binding
Biological process: signal transduction
Genetic constraint (gnomAD): Loss-of-function variants: 8 observed, 8.14 expected, observed/expected ratio (o/e) 0.98, 90% interval 0.57 to 1.7. That is too few expected variants to judge how well the gene tolerates losing a copy. Missense variants: 123 observed, 113.78 expected, observed/expected ratio (o/e) 1.08, 90% interval 0.93 to 1.26. Synonymous variants: 54 observed, 50.74 expected, observed/expected ratio (o/e) 1.06, 90% interval 0.85 to 1.34.
Homologues: Orthologues: mouse Gm49394 (58% identical).